MIR6859-2 (microRNA 6859-2)
Synonyms: hsa-mir-6859-2
Gene: MicroRNA gene on chromosome 1 (187,891 to 187,958, reverse strand). Ensembl gene ENSG00000273874.
Homologues: Paralogues in human: MIR6859-1 (100% identical), MIR6859-3 (100% identical), MIR6859-4 (100% identical).